ABCC6 (ATP binding cassette subfamily C member 6)
Diseases named in the same sentence as ABCC6 in open-access papers (continued):
Sharing a sentence is not in itself a finding about the gene and the disease.
myocarditis (1 paper, 2015). Myocarditis is a condition that is characterized by inflammation of the heart muscle (myocardium). "Several B6-specific myocarditis susceptibility loci have been identified, which may have affected the penetrance of Abcc6 in our complementation crosses." (PMID 26375467, 2015).
Obesity (1 paper, 2023). Accumulation of substantial excess body fat. "In addition, PAS-SNPs have also been identified in other obesity-related genes: Abcc6 and Npc1 in the Fat line and Lsamp (limbic system-associated membrane protein) in the Lean line, as well as in Arhgap8 (Rho GTPase activating protein 8) in the Fat line, which is localised in the dominant Fob2." (PMID 36414820, 2023).
osteoarthritis (1 paper, 2024). A noninflammatory degenerative joint disease occurring chiefly in older persons, characterized by degeneration of the articular cartilage, hypertrophy of bone at the margins and changes in the synovial membrane. "Interestingly, our analysis revealed several drugs that specifically target ABCC6, including one approved for osteoarthritis treatment." (PMID 39526184, 2024).
schizophrenia (1 paper, 2009). A major psychotic disorder characterized by abnormalities in the perception or expression of reality. "All three deletions included the region chr16:15387380–16198600 (and the genes MPV17L, c16orf45, KIAA0430, NDE1, MYH11, KIAA0866, c16orf63, ABCC1 and MRP6/AbCC6) indicating that a large deletion of this region may be a recurrent schizophrenia risk factor." (PMID 19197363, 2009).
thalassemia (1 paper, 2015). An inherited blood disorder characterized by a decreased synthesis of one of the polypeptide chains that form hemoglobin. "Indeed, perturbation of Abcc6 function was found in a β-thalassemia mouse model (Hbbth3/+), showing a progressive liver-specific downregulation of Abcc6 gene expression." (PMID 26356190, 2015).
triple-negative breast carcinoma (1 paper, 2023). An invasive breast carcinoma which is negative for expression of estrogen receptor (ER), progesterone receptor (PR), and human epidermal growth factor receptor 2 (HER2). "In patients with triple-negative breast cancer, the highest mean expression level compared to the normal tissue surrounding the tumor was noted for the ABCC3 gene (M = 0.038216), while the lowest mean expression level was recorded for the ABCC6 gene (M = −0.949418)." (PMID 36674773, 2023).
xanthoma (1 paper, 2023). A non-neoplastic disorder characterized by a localized collection of histiocytes containing lipid. "A patient with compound heterozygous ABCC6 mutations (p.W14X and p.M848fs) was diagnosed with PXE based on xanthoma and angioid streaks." (PMID 36261288, 2023).
cancer (19 papers, 2010 to 2025). A tumor composed of atypical neoplastic, often pleomorphic cells that invade other tissues. "Contrary to previous findings, it was also revealed that ABCC6 down-regulation is associated with enhanced treatment resistance in some cancers." (PMID 38003580, 2023). "Several studies have investigated the potential associations between ABCC6, cancer development, and multidrug resistance." (PMID 38003580, 2023). "We found that the TSIRS was negatively correlated with cancer stemness (mRNAsi) and positively correlated with the expression of multi-drug resistance associated protein (ABCC2, ABCC3, ABCC6 and ABCC10)." (PMID 36467413, 2022). "Functional studies further revealed that ABCC6 knockdown significantly enhanced cancer cell proliferation in vitro and in vivo." (PMID 35280774, 2022). "In conclusion, ABCC6 depletion inhibits peroxisome activity, protects cancer cells from oxidative damage, and therefore promotes cell proliferation." (PMID 35280774, 2022). "Involvement of ABCC6 in drug resistance in this type of cancer has been also reported, to some degree." (PMID 35645325, 2022). "In the present study, we analyzed the effect of Abcc6 knockdown and probenecid-induced ABCC6 inhibition on the extracellular ATP availability, and consequently on cell migration, an important cellular process correlated to cancer." (PMID 32517079, 2020). "Different roles of ABCC6 in various cancer types have been reported; it has been given an irrelevant, important, diagnostic or prognostic role." (PMID 32517079, 2020). "Our results showed significant upregulation in ABCB1, which is also known as multidrug resistance 1 (MDR1), ABCC6, and ABCG1, which were associated with cancer chemoresistance previously." (PMID 30832318, 2019). "ABCC6 is primarily expressed in the liver and kidney and confers resistance to a number of anti-cancer agents." (PMID 29385210, 2018). "It has been reported that the expression of ABCC1, ABCC3 or ABCC6 was upregulated in multi-drug resistant cancer." (PMID 29228716, 2017). "Furthermore, a change in cytoskeleton rearrangement and decreased motility of HepG2 cells makes ABCC6 a potential target for anti-cancer therapy." (PMID 33799762, 2021). "Since ABCC6 is a membrane transport protein important in the reduction of intracellular accumulation of cisplatin, the reduced amount of ABCC6 by kaempferol prevents the removal of cisplatin from the cell leading to the killing of the cancer cell by cisplatin." (PMID 20459793, 2010). "Both ABCC6 and ABCC7/CFTR have also been shown by others to harbor mutations that impair function and lead to disease, suggesting they may serve as cancer‐specific vulnerabilities." (PMID 40641097, 2025). "In addition, cell cycle analysis showed that ABCC6 knockdown significantly increased the percentage of cells in the G2/M phase and decreased the G0/G1 phase, suggesting that ABCC6 may regulate the cell cycle in cancer cells." (PMID 35280774, 2022). "Furthermore, ABCC6 could play a role in cancer cell biology as an ATP supplier of the purinergic pathway." (PMID 32517079, 2020). "On the contrary, in MDA-MB-231 cells, in which the expression of Abcc6 was from low to negligible compared to HepG2 cells, probenecid did not affect the extracellular ATP content, thus suggesting that the ABCC6 transporter is scarcely involved in the extrusion of ATP from these cancer cells." (PMID 32517079, 2020). "ABCC6 and ABCC7 were identified as strongly selective genes, underscoring their potential as cancer‐specific vulnerabilities." (PMID 40641097, 2025). "In addition to P-gp and MRP1, other ABC transporters such as MRP6 (ABCC6), MRP2 (ABCC2), MRP7 (ABCC10), and MRP3 (ABCC3) also contribute to the development of drug resistance in various cancers." (PMID 39679367, 2024).
cancer (continued). "Cellular model studies have shown that ABCC6, which belongs to the ABC subfamily C (ABCC), plays a role in the cytoskeleton rearrangement and migration of HepG2 hepatocarcinoma cells, thus highlighting its role in cancer biology." (PMID 38003580, 2023). "The low ability of ABCC6-silenced cells to invade the Matrigel was most likely due to the reduced expression and secretion of active forms of the two metalloproteinases MMP2 and MMP9, whose activities have been correlated with the invasive stage of carcinomas." (PMID 38003580, 2023). "Moreover, seahorse assay showed that ABCC6 depletion affected the cellular energy phenotype and mitigated the oxygen consumption rate (OCR) of cancer cells under stress conditions, most likely due to the lower lipid peroxidation activity." (PMID 35280774, 2022). "Moreover, in both knockdown and probenecid-treated HepG2 cells, the expression of lamin was found decreased, which suggests that reduced ABCC6 transport activity also leads to cell senescence in PXE and can be beneficial to prevent cancer progression." (PMID 33799762, 2021). "Because kaempferol sensitizes OVCAR-3 cancer cells' response to cisplatin treatment, the effect on gene expression by cisplatin and/or kaempferol was further evaluated by analyzing mRNA levels of ABCC1, ABCC5, ABCC6, NFκB1, cMyc and CDKN1A genes." (PMID 20459793, 2010).
genetic disorder (14 papers, 2009 to 2025). "In humans, dystrophic cardiac calcinosis (DCC) is a genetic disorder caused by mutations in Abcc6 with ectopic calcifications in various tissues, including the heart." (PMID 40471241, 2025). "PXE is a recessive genetic disorder, marked by mutations in ABCC6, that affects the skin and connective tissues, including ocular structures." (PMID 34394872, 2021). "This genetic disorder, caused by mutations in the transporter gene ABCC6, is characterized by alterations in the extracellular matrix, especially in the skin, retina, and the vascular system." (PMID 19828023, 2009). "Furthermore, some cases of generalized arterial calcification of infancy (GACI), which is a rare genetic disease with early-onset and life-threating ectopic calcifications, are caused by Abcc6 mutations." (PMID 40471241, 2025). "PXE is a rare inherited genetic disorder mainly caused by mutations in the ABCC6 gene." (PMID 32489700, 2020). "PXE is a genetic disorder for which nearly no genotype-phenotype correlations exist between the causal gene ABCC6 and the eye, skin and cardiovascular features." (PMID 34169069, 2021).
metabolic disease (14 papers, 2012 to 2025). A congenital disorder (due to inherited enzyme abnormality) or acquired (due to failure of a metabolically important organ) disorder resulting from an abnormal metabolic process. "Some studies suggest that mutations of ABCC6 in the liver lead to a decrease in some circulating factor and indicate that PXE is a metabolic disease." (PMID 33799762, 2021). "Although PXE is considered an ABCC6‐mediated metabolic disease, these results strongly suggest that an inflammatory process could participate in the pathophysiology of PXE." (PMID 39624746, 2024). "Concurrent with this hypothesis, a recent study shows that abrogated ABCC6 function causes alterations in the metabolic profile of the liver, which aligns with the concept of PXE being a metabolic disease originating from liver disturbance." (PMID 28536638, 2017). "Mutations and deletions in ABCC6 are known to cause the rare (prevalence between 1:25,000 and 1:100,000), autosomal recessive disease pseudoxanthoma elasticum (PXE, OMIM 264800), a metabolic disorder characterized by ectopic mineralization of soft connective tissues." (PMID 22873774, 2012). "Previous studies of serum analysis either from the ABCC6 knock-down mouse model or from PXE patients showed an inability to prevent calcium and phosphate deposition and suggested that PXE is a metabolic disease with very slow onset." (PMID 33799762, 2021). "Because of the predominant expression of ABCC6 in liver and kidney, PXE is considered a metabolic disorder driven by the absence of systemic substrates provided from the liver through ABCC6." (PMID 36902680, 2023). "Hence, on the basis of experiments in HEK293 cells overexpressing either human or rat ABCC6 and in vivo experiments in Abcc6(−/−) mice, PPi has been proposed as the candidate circulating factor involved in PXE metabolic disease." (PMID 28486967, 2017). "The second, predominant paradigm for PXE is that of a systemic, metabolic disease in which the lack of production or release of one or more circulating factors from the liver (where ABCC6 is usually most strongly expressed) leads to ectopic mineralization." (PMID 28486967, 2017). "Interestingly, ABCC6 is predominantly expressed in the liver tissue, leading to the hypothesis that PXE is a metabolic disorder." (PMID 40277901, 2025).
tumor (13 papers, 2008 to 2025). "NGS analysis of the three tumors showed that three genes, namely, RIMS3, LOC283710, and ABCC6, with the same somatic mutation, were present in each tumor of the same individual." (PMID 35912179, 2022). "Hypermethylation was associated with advanced tumor stage for ABCC6 (P = 0.050), BRCA1 (P = 0.032), CDH1 (P = 0.004), GDF15 (P = 0.005), HSPA2 (P = 0.000), RASSF1A (P = 0.003), TSHB1 (P = 0.018), and TMEFF2 (P = 0.002)." (PMID 25613404, 2015). "Consistent with our bioinformatic analysis, this assessment also showed significantly lower ABCC6 expression in tumor tissues than in paratumor tissues, suggesting that ABCC6 might be a potential diagnostic marker in HCC." (PMID 35280774, 2022). "The results showed that the tumor biopsy presented high ABCC6 and ABCC10 expression, and metastasis presented high ABCB1 expression when metastasis was present at diagnosis." (PMID 36982681, 2023). "To further study the role of ABCC6 in tumor biology, we knocked down or overexpressed ABCC6 in HCC cells and evaluated their migration ability." (PMID 35280774, 2022). "It was observed in the TCGA database that ABCC1, ABCC4, ABCC5, and ABCC10 were significantly upregulated in tumor tissues, while ABCC6 and ABCC7 were downregulated in HCC tissues." (PMID 35342392, 2022). "As expected, tumor size, tumor growth curve, and tumor weight were substantially augmented following ABCC6 knockdown, indicating that ABCC6 depletion also facilitates tumor progression in vivo." (PMID 35280774, 2022). "Taken together, these data suggest that ABCC6 plays a tumor-suppressive role by inhibiting HCC proliferation in vitro." (PMID 35280774, 2022). "Collectively, our data suggest that ABCC6 is downregulated in HCC tumor tissues and correlates with favorable outcomes in patients with HCC." (PMID 35280774, 2022). "In this study, we evaluated the expression level and prognostic prediction value of all ABC transporter family members in TCGA and GSE14520 datasets, and found that ABCC6 is significantly downregulated in HCC tumor tissues and correlated with favorable outcomes in patients with HCC." (PMID 35280774, 2022). "Moreover, western blotting assays confirmed lower ABCC6 expression in tumor tissue than in paratumor tissues." (PMID 35280774, 2022). "Consistently, ABCC6 was significantly downregulated in tumor tissues compared to paratumor tissues." (PMID 35280774, 2022). "Furthermore, the intricate interplay between all the pathways regulated by ABCC6 and the dysregulated genes could allow us to hypothesize about using other molecules with anti-tumor activity in combination with ABCC6 inhibitors." (PMID 38003580, 2023). "Mutations in RIMS3, LOC283710, and ABCC6 genes do not cause tumor formation, suggesting that they might be passenger mutations." (PMID 35912179, 2022). "However, the role of ABCC6 in tumor biology has been poorly investigated." (PMID 35280774, 2022). "However, our study is the first to report ABCC6 expression in NE tumour cells." (PMID 18827820, 2008). "Our previous studies have identified ABCA6, ABCC6 and ABCG5 as potential tumor-suppressor genes in HCC." (PMID 35280774, 2022). "Statistical analysis performed with the U Mann–Whitney test showed a statistically significantly higher expression level of the ABCB9 (p = 0.000), ABCC1 (p = 0.009), and ABCC6 (p = 0.000) genes in patients without tumor cell invasion into fat tissue." (PMID 36674773, 2023). "Consistent with our findings, a previous study also demonstrated that the ABCC6 protein was highly expressed in liver tissue, but remained non-detectable in a small panel of human tumor samples." (PMID 35280774, 2022). "Furthermore, we measured the expression of ABCA6, ABCC6, and ABCG5 in 50 pairs of early-stage tumor tissues and paratumor tissues using quantitative reverse transcription polymerase chain reaction (qRT-PCR)." (PMID 35280774, 2022).
tumor (continued). "The average expression level of the ABCA3 (p = 0.007), ABCB9 (p = 0.000), ABCC1 (p = 0.000), ABCC4 (p = 0.000), ABCC5 (p = 0.000), and ABCC6 (p = 0.000) genes was statistically significantly higher in patients without tumor cell infiltration in the lymph vessels." (PMID 36674773, 2023). "First, it does not address why ABCC6 is downregulated in tumor tissues." (PMID 35280774, 2022). "Multivariate Cox regression analysis of clinical prognostic information demonstrated that downregulated ABCC6 was not only an independent prognostic marker, but also correlated with some malignant and aggressive clinicopathological features, such as high AFP values and large tumor size." (PMID 35280774, 2022).
connective tissue disorder (10 papers, 2013 to 2025). A disease involving the connective tissue. "Mutations in the ABCC6 gene were proved to be responsible for connective tissue disorder and suggested to play a role in the transportation of toxic metabolites to which connective tissue cells are sensitive." (PMID 33490088, 2020). "Despite marked structural resemblance with other ABC transporters, ABCC6 has been considered the odd man out, due to its unique relation with a connective tissue disease affecting tissues in which it is hardly expressed." (PMID 24137173, 2013). "Unique in the group of connective tissue disorders, the pathophysiological relation between the ABCC6 transporter and ectopic mineralization in PXE remains enigmatic, not in the least because of lack of knowledge on the substrate(s) of ABCC6 and its unusual expression pattern." (PMID 24137173, 2013).
cardiovascular disease (7 papers, 2013 to 2025). "In a large multigenerational family, the pathogenic ABCC6 variant (p.[Arg1314Gln]) was segregated alongside cerebrovascular and cardiovascular diseases." (PMID 40725385, 2025). "Heterozygous carriers of one ABCC6 pathogenic variant have previously been shown to be more prone to cerebro- and cardiovascular diseases, while it was previously suggested that carriers in rare cases can also develop a PXE retinopathy." (PMID 39329949, 2024). "In conclusion, the impact of ABCC6 variants as a genetic risk factor for common cardiovascular diseases remains to be elucidated." (PMID 23802012, 2013). "Variants in the ENPP1, ABCC6 and 5'-nucleotidase ecto (NT5E) genes, which are involved in metabolism of PPi and Pi, have been found to predispose to coronary arterial, valvular calcification and other cardiovascular diseases." (PMID 35387434, 2022).
infection (2 papers, 2015 to 2024). The state of being infected such as from the introduction of a foreign agent such as serum, vaccine, antigenic substance or organism. "The increased necrosis despite equal viral titer observed in Abcc6 deficient mice suggested the existence of a pathologic host response to infection." (PMID 26375467, 2015). "We demonstrated an accumulation of hydroxyappatite in the mitochondria of Abcc6 KO mice following infection." (PMID 26375467, 2015). "Upon infection, levels of calcium in Abcc6 WT hearts remained constant with infection whereas levels in Abcc6 KO hearts increased drastically with infection." (PMID 26375467, 2015). "We next evaluated calcium levels in two genetic complementation groups, (Abcc6 KO x 129S1)F1 and (Abcc6 WT x 129S1)F1 mice, at days 0 and 8 post infection." (PMID 26375467, 2015). "To exclude the possibility that these observations arose due to an independent background effect, we evaluated viral titer and necrosis in Abcc6 KO and WT/Het mice at day 8 post-infection." (PMID 26375467, 2015). "Hearts from uninfected and infected (day 6 post infection) Abcc6 WT and KO mice were excised, sectioned, and stained for TEM." (PMID 26375467, 2015). "We first evaluated calcification in Abcc6 KO, Het and WT mice at days 0 and 8 post infection." (PMID 26375467, 2015).